TIMD4 (T cell immunoglobulin and mucin domain containing 4)
Diseases named in the same sentence as TIMD4 in open-access papers (continued):
Sharing a sentence is not in itself a finding about the gene and the disease.
periodontitis (1 paper, 2024). An acute or chronic inflammatory process that affects the tissues that surround and support the teeth. "The noticeably greater alveolar bone resorption was detected in Timd4−/− mice as compared with wild type mice after the establishment of periodontitis." (PMID 38418808, 2024). "Further analysis of H&E staining substantiated the more serious alveolar bone resorption in Timd4−/− mice after periodontitis induction (black dotted area)." (PMID 38418808, 2024). "Both specifically expressed in macrophages, Cd301b and Timd4 displayed largely overlapped expression patterns, indicating that Tim4 might serve as a promising target of CD301b+ macrophages in periodontitis." (PMID 38418808, 2024). "Staining and flow cytometric analysis of macrophages in periodontal tissue elucidated that the percentages of CD301b+ macrophages in Timd4−/− mice were significantly reduced compared with wild type mice among the groups without periodontitis." (PMID 38418808, 2024).
renal carcinoma (1 paper, 2025). A carcinoma arising from the epithelium of the renal parenchyma or the renal pelvis. "However, our study has certain limitations, such as not investigating the specific molecular mechanisms by which TIMD4 promotes renal cancer progression, which can be further validated through molecular biology experiments in the future." (PMID 40576208, 2025).
tumor (97 papers, 2013 to 2026). "TIMD4 on tumour‐associated macrophages (TAMs) can mediate the degradation of apoptotic tumour cells, thereby enhancing the reactivity of APCs and CTLs, ultimately weakening the efficacy of anti‐tumour chemotherapy." (PMID 40576208, 2025). "CD81 promoted the production of PCS, which not only regulated tumour growth but also enhanced the mitophagy of T cell immunoglobulin and mucin domain containing 4 (Tim4) positive tumour‐associated macrophages (TAMs)." (PMID 40604335, 2025). "TIMD4 expression in tumour‐associated myeloid cells such as macrophages and dendritic cells promotes autophagy of dying cancer cells and leads to attenuated antigen presentation and increased immune tolerance." (PMID 38633121, 2024). "Cell function experiments, on the other hand, validated TIMD4 as a tumor risk factor in GBM." (PMID 37853449, 2023). "Small molecule drugs targeting TIMD4, when combined with other anti‐tumour agents, hold promise as a new cancer treatment strategy." (PMID 40576208, 2025). "The results of the CCK‐8 assay also indicated that the knockdown of TIMD4 inhibited the proliferation of tumour cells, with a more pronounced inhibitory effect on the proliferation of the ACHN cell line." (PMID 40576208, 2025). "Previous studies have indicated that the expression of TIMD4 is limited to antigen‐presenting cells; however, it has now been found to be expressed in various tumour cells." (PMID 40576208, 2025). "Overall, TIMD4 can be used as an important biomarker for tumour prognosis and immunotherapy response, providing new insights into the mechanisms of tumour immune microenvironment and progression, as well as a novel therapeutic target." (PMID 40576208, 2025). "During literature investigation, we identified significant research gaps regarding TIMD4's tumour biological functions and pharmacological development." (PMID 40576208, 2025). "The results showed that the tumour size in the TIMD4 knockdown group was significantly smaller than that in the NC group, indicating that TIMD4 can also regulate the proliferation of ACHN cells in vivo." (PMID 40576208, 2025). "We found that TIMD4 plays a role in antigen‐presenting cells and can also be expressed as a cancer‐promoting factor in tumour cells, affecting the prognosis of patients." (PMID 40576208, 2025). "We found that TIMD4 expression was significantly higher in tumour cells than in normal cells, both at the protein and gene levels." (PMID 40576208, 2025). "Recent data from tumour experimental models have shown that blocking TIMD4 can enhance the anti‐tumour efficacy of immune checkpoint inhibitors (ICI, anti‐PD1) and adoptive T‐cell (ACT) therapies in mouse models." (PMID 40576208, 2025). "We then employed Transwell and wound healing assays to assess the effect of TIMD4 on the migratory capacity of tumour cells." (PMID 40576208, 2025). "Our results showed that FAM30A or TIMD4 expression was upregulated in tumor tissues compared with paired corresponding normal tissues (P < 0.001)." (PMID 34476011, 2021). "Most importantly, containment of tumor growth was reduced in Timd4−/−:Batf3−/− chimeras as shown by more abundant lesions and larger nodules than in animals reconstituted with wild-type:Batf3−/− bone marrows." (PMID 33854047, 2021). "Additionally, we conducted small molecule drug screening for the TIMD4 gene, which has been rarely studied in tumour cells." (PMID 40576208, 2025). "In summary, TIMD4 plays an important regulatory role in the tumour immune microenvironment and may become a significant target for tumour immunotherapy and chemotherapy in the future." (PMID 40576208, 2025). "Silencing TIMD4 effectively inhibited the proliferation and migration of tumour cells." (PMID 40576208, 2025). "We presuppose here (based on the mechanism of action of TIMD4) that high PD-L1 expression could have influenced the TME to induce downregulation of circulating TIMD4 as an active anti-tumor response mechanism in responding patients." (PMID 37256148, 2023).
tumor (continued). "Several were most upregulated in specific subsets, such as multi-cytokine in CD8 memory; TIMD4/TIM3 in CD8 CM and γδT; CTLA4/CD38 in Treg, CD4 memory and CD8 CM; and OX40/EBI3 in tumor-infiltrating T cells." (PMID 40903640, 2025). "Considering the findings for M-MDSC, ARG1, soluble VISTA, Treg cells, IL-10, and soluble TIMD-4, it can be suggested that immunosuppression at the periphery has a significant impact, sustaining impaired systemic immunity, which may limit the anti-tumoral immune response at the tumor site." (PMID 39502689, 2024). "Simultaneous infection of stromal and tumor cells; Upregulation of Fez1 and Pycard; Downregulation of DLL-4, Angiopoietin 2, PECAM, Tie-1, and FOS EGR2, CREB-5, IL-6, Map2K1, CCL22, TIMD4 and CCL19." (PMID 35640930, 2022). "Timd4 (T-cell immunoglobulin domain and mucin domain 4; also known as TIM4) plays a critical role in regulating tumor immunosurveillance and anti-tumor immunity." (PMID 34517344, 2021). "Moreover, in mice, T cell immunoglobulin and mucin domain containing 4 (TIMD4, better known as TIM4), the phosphatidyl serine receptor, facilitates antigen uptake by tissue-resident lung cDC1s, thus driving tumor immunosurveillance." (PMID 37907944, 2023). "Additionally, we compared the expression levels of TIMD4 in HA cells and three GBM cell lines by cell line experiments and found that BARD1 was significantly highly expressed in tumor cells, especially SW1783 cells." (PMID 37853449, 2023). "In addition, TIMD4 expression was not significantly different between tumor samples and normal tissues and not correlated significantly with OS of patients (p = 0.142)." (PMID 40519919, 2025).
cancer (47 papers, 2017 to 2026). A tumor composed of atypical neoplastic, often pleomorphic cells that invade other tissues. "Although the mechanism of TIMD4-mediated cancer progression remains unknown, the study showed that mutation in the TIMD4 RGD motif reduces cancer progression." (PMID 37256148, 2023). "It is important to note that Il1rap, Ifi44, Timd4, Fabp3, and Eno 2 have been reported as potential therapeutic targets and potential prognostic biomarkers for several cancers." (PMID 41011134, 2025). "Based on currently published studies, we found that the functions and cancer regulatory mechanisms of seven ECGs, excluding TIMD4, have been elucidated." (PMID 40576208, 2025). "Recently, AXL and TIMD4 have also been reported to be positively correlated to the poor progression of many cancers." (PMID 34778091, 2021). "We further investigated the impact of TIMD4 on the biological behaviour of cancer cells." (PMID 40576208, 2025). "Finally, four key genes (KLHL30, PLN, LYVE1, and TIMD4) and four clinical factors (Asian, age, grade, and bilirubin) were included in the prognostic model, namely Immunity and Cancer-stem-cell Related Prognosis (ICRP) score." (PMID 32852285, 2020). "We also validated the LC substrate candidates CLMP, ICAM1, PCDH17, as well as the cancer-related GPNMB and TIMD4 as substrates." (PMID 40593564, 2025). "Subsequently, we analysed the expression levels of these genes across 33 types of cancer and found that AXL, MERTK, TYRO3, CD24, HAVCR2 and CD47 exhibited higher expression levels, while TIMD4 and HAVCR1 showed relatively lower expression." (PMID 40576208, 2025).
infection (31 papers, 2013 to 2026). The state of being infected such as from the introduction of a foreign agent such as serum, vaccine, antigenic substance or organism. "Indeed, pmacs from Timd-4-/- mice were more sensitive to the effects of M2a polarization with ~50-fold increase in infection observed in the polarized cells, an effect that was only observed with rVSV/EBOV GP and not with rVSV/G." (PMID 31825972, 2019).
TIMD4 also shares sentences with these, for which no sentence is quoted: Allergy (10 papers); Obesity (9); liver fibrosis (7); colon carcinoma (5); asthma (4); breast cancer (4); diffuse large B-cell lymphoma (4); food allergy (4); lupus (4); nonalcoholic fatty liver disease (4); dendritic cell neoplasms (3); Hepatitis (3); liver (3); liver cancer (3); ovarian tumour (3); acute monocytic leukemia (2); allergic rhinitis (2); cognitive deficits (2); colitis (2); dengue (2); endometriosis (2); fibrosis (2); histiocyte sarcoma (2); ischaemic stroke (2); ischemia (2); Langerhans cell histiocytosis (2); metabolic disease (2); nasal polyp (2); Non-alcoholic steatohepatitis (2); Pleural effusion (2).
A further 54 diseases each share a sentence with TIMD4 in 2 papers or fewer.